DKK1 (dickkopf Wnt signaling pathway inhibitor 1)
Diseases named in the same sentence as DKK1 in open-access papers (continued):
Sharing a sentence is not in itself a finding about the gene and the disease.
tumor (continued). "The Dkk1-CKAP4 signalling axis can drive cell proliferation and Dkk1 as well as CKAP4 are upregulated in tumours." (PMID 35279766, 2022). "Using a murine model of a Dkk-1 expressing OS, we demonstrated that DkkMo reduces tumour progression through reduction of cell proliferation, perturbation of survival mechanisms, inhibition of bone destruction, and through depletion of the tumour stroma." (PMID 35277659, 2022). "In the tumor microenvironment, CCA cells DKK1 (paracrine dickkopf-related protein 1) to enhance the angiogenic potential of tumor-associated endothelial cells." (PMID 36147461, 2022). "Treating tumor cells with Dkk-1 upregulated FGF-13, PLCB1, and MYC gene expression, which are key components in Ras, PI3K-MAPK, and Wnt signaling pathways." (PMID 36439519, 2022). "Despite DKK1 expression, Wnt signaling was found to be active in these cells due to the downregulation of DKK1 receptors, a phenomenon that was suggested as a mechanism of DKK1 resistance in osteolytic-lesion-forming tumor cells." (PMID 36497192, 2022). "Co-implantation with BCSCs decreases the tumor-initiating capacity yet increases metastasis of accompanying cancer cells, wherein DKK1 is identified as a pivotal factor secreted by BCSCs for such functions." (PMID 35296660, 2022). "MSCs can block Wnt signaling by regulating the Dickkopf-related protein 1 (DKK1) secreted by tumor cells, downregulating c-Myc and Cyclin D2 and upregulating the expression of P21CIP1 and P27KIP1, resulting to tumor cell suppression." (PMID 36225602, 2022). "DKK1 has been reported to modulate tumor metastasis by dictating the NK cells, macrophages or neutrophils in the tumor microenvironment." (PMID 35296660, 2022). "The data indicated that DKK1 protein expression was descended and β-catenin protein expression was enhanced in the tumor tissues compared to that in the paired normal lung tissues." (PMID 35907982, 2022). "We aimed to analyze the role of DKK1 or β-catenin as a prognostic factor in BTC, and determine the clinical associations of ß-catenin and DKK1 with CD8+ tumor-infiltrating lymphocytes (TIL)." (PMID 35121803, 2022). "The expression level of DKK1 is increased in the tumor tissues and serum samples of PC patients, and its detection facilitates the diagnosis of early-stage PC." (PMID 34993253, 2021). "Preclinically, DKK1 was proven to promote proliferation, metastasis, and invasion in cancer cell lines and DKK1 inhibition showed efficacy on tumor regression in animal models." (PMID 34093545, 2021). "We developed an image analysis algorithm to identify tumor cells, quantify the amount of DKK1 signal by numbers of dots per cell, and finally calculate a digital H-score." (PMID 33972574, 2021). "As expected, the miR-33a-5p expression was up-regulated and DKK1 expression was down-regulated by miR-33a-5p-mimic in the tumor tissues of the mice." (PMID 34426559, 2021). "While miR-140-5p and miR-185 target Wnt1 and act as tumor suppressors, miR-410 targets Dkk1 and thus functions as an oncogene in CRC." (PMID 33585487, 2021). "Previous studies demonstrated that DKK1 was correlated with accumulation of myeloid-derived suppressor cells in PC, contributing to the suppression of the responses of anti-tumor T cells." (PMID 34143198, 2021). "TNC downregulated Dick-kopf-1 (DKK1), a Wnt inhibitor by blocking of actin stress fiber formation, thus activating Wnt signaling and induced Wnt target genes in tumor and endothelial cells." (PMID 34615554, 2021). "Taken together, these results indicate that the digital image solution is specific, sensitive, accurate, and precise for DKK1 RNAscope staining of G/GEJ tumor tissue." (PMID 33972574, 2021). "The therapeutic strategy of developing a combination of DKK1 and immune checkpoint inhibitor based on precision medicine is promising for tumor patients with high DKK1 expression." (PMID 34093545, 2021).
tumor (continued). "As part of the formal validation following CLIA guidelines, DKK1 staining was shown to be localized to tumor cells in G/GEJ resections with a wide dynamic signal range, therefore demonstrating specificity and sensitivity." (PMID 33972574, 2021). "Most research has indicated a DKK1 inhibitory effect in tumors, but interestingly, some studies showed DKK1′s tumor-promoting role." (PMID 34064046, 2021). "As DKK1 is a potent inhibitor of Wnt signaling it was originally characterized as a tumor suppressor, however, recent research identified DKK1 expression as a negative prognostic marker in several cancer entities." (PMID 34638464, 2021). "DKK1 has been shown to cause inflammation and to promote cell migration and invasion in HCC through TGF-β1-mediated remodeling of tumor microenvironment." (PMID 33562077, 2021). "Many researches have suggested the tumorigenic effect of DKK1, while others have showed that DKK1 acts as a tumor suppressor." (PMID 33969120, 2021). "In order to initially assess a digital approach, 6 G/GEJ tumor tissues with a range of DKK1 expression, were digitally scored in duplicate and compared to manual duplicate scoring by two separate pathologists." (PMID 33972574, 2021). "Dkk-1 contributed to tumor growth through the regulation of Wnt signaling and PI3K/AKT signaling in cancer cells." (PMID 34437475, 2021). "We specifically selected the mean values of normalized DKK1 TPM mRNA to do the Student’s t-test to verify the differential expression pattern in various tumor types." (PMID 34093545, 2021). "Some research suggests that DKK1 acts as a tumour suppresser by inhibiting cancer cells’ proliferation and metastasis." (PMID 33670440, 2021). "On the other hand, a novel anti-tumor DNA vaccine designed by Guo’s team stressed the significance of the role of CD8+ cells in the effect of DKK1 on tumor immunosuppression." (PMID 34093545, 2021). "In CRC, high DKK1 expression levels correlate with lower tumor stages, less metastasis, and increased five-year survival of patients." (PMID 35008201, 2021). "Due to the inhibitory function of DKK1 in β-catenin-dependent Wnt signaling, which was a frequently overactivated pathway in cancer, DKK1 was originally characterized as a tumor suppressor." (PMID 34093545, 2021). "The combination of both S100A4 and DKK1 clearly improves the prognostic value in CRC compared to each tumor marker alone." (PMID 35008201, 2021). "Sensitivity of the assay was confirmed by detecting tumor cells with a range of DKK1 expression, including cells with only a single dot which corresponds to one molecule of RNA25." (PMID 33972574, 2021). "DKK1, a regulator of Wnt signaling, is found to affect the tumor microenvironment by suppressing tumor immunity and can be used as an immunotherapeutic target for OC, which is consistent with our research results." (PMID 35087563, 2021). "DKK1 expression promoted cancer cell expansion and increased tumor stress metabolic resistance for its upregulation of ALDH levels." (PMID 34093545, 2021). "Meanwhile, in terms of tumor growth, DKK-1 inhibits the activation of Wnt signaling to influence GC growth by suppressing cancer stem cells." (PMID 33987183, 2021). "Silencing of DKK1 reduced tumor growth rate, tumor volume, and vasculogenic-related protein expression." (PMID 34093545, 2021). "DKK1 responded to the treatment of anti-DKK1 antibody BHQ880 with decreased tumor growth rate and metastasis." (PMID 34093545, 2021). "In this study, antibody-mediated neutralization of DKK1 resulted in a marked reduction of MDSCs expansion and tumor progression." (PMID 34093545, 2021). "Anti-tumor efficacy of anti-DKK1 DNA vaccine in mice model required the function of CD8+CD11c+ dendritic cells (DCs) and CD8+ T cells." (PMID 34093545, 2021). "In turn, we found a significant increase of DKK1 protein expression in the tumor tissues with reduced S100A4 expression (median = 35.94), compared to control treatment (median = 27.54, p = 0.024)." (PMID 35008201, 2021).
tumor (continued). "High S100A4 and low DKK1 expression levels in the primary tumor resulted in a five-year MFS of 29% (±17.1%)." (PMID 35008201, 2021). "Here we report on the validation of a DKK1 RNAscope chromogenic in situ hybridization assay to assess DKK1 expression in G/GEJ tumor tissue." (PMID 33972574, 2021). "DKK1 induces angiogenesis through Wnt/β-catenin-dependent or Wnt/β-catenin-independent mechanisms in tumor cells." (PMID 34803487, 2021). "Next, we determined the mRNA levels of S100A4 and DKK1 in micro-dissected primary tumor tissues of two independent patient cohorts by gene-specific qRT PCR." (PMID 35008201, 2021). "If patients expressed low levels of S100A4 and high levels of DKK1 in the tumor, the five-year survival was 90% (±7.0%) in the first cohort and 91% (±6.1%) in the second cohort." (PMID 35008201, 2021). "For a majority of the tumor tissues, DKK1 tumoral expression was quantified digitally by morphometric analysis and an H-score was calculated by determining the percentages of tumor cells expressing low, medium, and high levels of DKK124." (PMID 33972574, 2021). "Although there has been a more detailed and clear description of the participation of DKK1 in immune response due to recent research, an investigation of how DKK1 manipulates different immune responses to exert anti-tumor effects is necessary." (PMID 34093545, 2021). "A region of analysis (ROA) that contained viable tumor cells and sufficient PPIB signal (≥ 4 dots/cell) was annotated for DKK1 scoring and manually assigned an H-score for the tumor cells." (PMID 33972574, 2021). "DKK1 is well known for its roles in the regulation of the tumor microenvironment and immune response by the Wnt pathway, and has been reported as an independent unfavorable prognostic indicator of HNSCC survival." (PMID 34220923, 2021). "DKK1 is differentially expressed in different types of human cancers, and its expression affects cell invasion, proliferation, and tumor growth." (PMID 34064046, 2021). "DKK-1 was originally described as a tumor suppressor by blocking the b-catenin dependent Wnt signaling pathway, which is frequently overactivated in cancer." (PMID 34944992, 2021). "Differentially expressed analysis of DKK1 between Tumor and Normal samples in Pan-cancer Texts in red indicate carcinomas with significant higher DKK1 expression level compared to normal sample (P<0.05)." (PMID 34093545, 2021). "High DKK1 expression in the tumor tissue or microenvironment seems to compensate for the aggressive phenotype of elevated S100A4 expression in OS." (PMID 35008201, 2021). "Another intriguing point in the clinical results is that in the combination treatment with DKN-1 and pembrolizumab, patients with a high DKK1 level in tumor demonstrated relatively higher efficacy than those with a low level." (PMID 34093545, 2021). "Owing to the reduction of invasion observed in vitro with WAY-262611, we next analyzed the possible role of DKK-1 inhibition in early metastasis steps in vivo, specifically the viability of tumor cells in lung tissue after the tail-vein injection was measured." (PMID 34884726, 2021). "Several of the top downregulated genes are bona fide or presumed tumor suppressor genes, including Dkk1 and Dkk3 (Wnt signaling antagonists)." (PMID 34638267, 2021). "Based on these results and the increasing evidence of DKK1 tumor promoting activity, further clinical development is warranted." (PMID 34093545, 2021). "DKK-1 is reported to be over expressed in GC patients and recently, it was reported to play different roles in the tumor growth due to different tumor environment." (PMID 33987183, 2021). "DKK1 enhanced tumor cell invasion and promoted lymph node metastasis through the induction of MMP9 and VEGF-C." (PMID 34093545, 2021). "Inhibiting DKK-1 activity by utilizing RNAi or neutralizing anti-DKK-1 antibodies results in reduced inhibitory impacts of MSCs on tumor cell proliferation." (PMID 33472580, 2021).
tumor (continued). "In regards with the size of the tumour, most of the cases were more than 5 cm which possibly means more extended disease, so it is easier to identify miR-33a-5p, DKK1 levels in the serum or tissue." (PMID 34426559, 2021). "According to gene profile analysis, mRNA level of DKK1 was overexpressed in a range of tumor types (14 out of 27)." (PMID 34093545, 2021). "It was suggested that the inhibitory nature of DKK-1 can be directly influenced by a tumor suppressor gene or indirectly via the induction of myeloid-derived suppressor cells." (PMID 32041953, 2020). "Our translational analysis based on the expression levels of ITF2 and DKK1 genes in two different cohorts of patients was aimed to elucidate the role of this pathway in tumor progression and chemotherapy response." (PMID 32224864, 2020). "Each tumor cell type is distinguished by the involvement of typical biological factors (e.g., DKK-1, Wnt, and PSA in PC and IL-6 plus VLA-4/VCAM-1 pathway in MM)." (PMID 33224935, 2020). "Wnt signalling promotes G1-S transition through Cyclin E1 and D1, and c-myc and Dikkopf-1 (DKK1), a Wnt signalling inhibitor, has been reported to promote tumour dormancy through an autocrine, but probably also paracrine signalling network." (PMID 32527062, 2020). "When the metastatic cancer cells colonized into brain, the decline of Dkk-1 would remove the limitation of immune suppression on microglia and facilitate them to acquire a tumor-supportive phenotype." (PMID 33384994, 2020). "The differential expression of DKK1 within the tumor samples allowed us to perform three different bioinformatics contrasts in order to explore all the possibilities regarding tumor development and the Wnt signaling pathway." (PMID 32224864, 2020). "Our meta-analysis did not highlight any dramatic changes in gene expression for the FZD7 and DKK1 genes between normal and tumor tissue." (PMID 32403323, 2020). "Among these DEGs several genes with oncogenic and/or metastasis promoting function (e.g. STC1, YES1, PORCN) were found to be down-regulated and certain tumour suppressor genes (e.g. DKK1, PERP) showed overexpression in LINC00152-silenced cells." (PMID 32307642, 2020). "In fact, a recent report by Zhuang and colleagues shows that DKK1-high tumours preferentially metastatise to bone, while DKK1-low tumours tend to migrate to the lungs." (PMID 32527062, 2020). "For example, Dkk1 derived from stromal cells within the tumor has been shown to downregulate β-catenin in myeloid-derived cells, leading to a suppressed T-cell response and tumor growth." (PMID 33126517, 2020). "More importantly, the decline of Dkk-1 expression had been also observed in the brain metastatic lesions compared to the primary tumor tissues in lung." (PMID 33384994, 2020). "Binding of GATA6 to the DKK1 promoter lead to a down-regulation of DKK1 and thus to a consecutive activation of the Wnt pathways and tumor progression." (PMID 32075129, 2020). "DKK1 showed a significant correlation with tumor size, liver dysfunction, and poor performance status in HCC patients." (PMID 31649806, 2019). "Taken together these data show the relevance of the Wnt signalling inhibitors of SOST and DKK-1 for implantology and bone augmentation, as well as for tumor development and cancer therapy." (PMID 31031968, 2019). "DKK1 seems to fulfill very contradictory functions in the tumorigenesis process, acting either as an oncogenic promoter of metastasis or as a tumor suppressor, depending on the cell type and context." (PMID 31568519, 2019). "Future studies will show how effective targeting of SOST and DKK-1 can be applied to stimulate regeneration and for tumor therapy." (PMID 31031968, 2019). "Another important finding of this study is that the tumor-suppressive activity of miR-376a in OS is due to DKK1 downregulation." (PMID 31525734, 2019).
tumor (continued). "The possible mechanism of tumor inhibition via naïve MSCs was attributed to the soluble factors secreted by these cells, including Dickkopf-related protein 1 (DKK1), which plays a role in the inhibition of Wnt signaling pathways in tumor cells." (PMID 31555593, 2019). "The upregulation of DKK1 mRNA negatively correlated with miR-376a levels among these OS tumor samples (r = -0.6236, P < 0.0001)." (PMID 31525734, 2019). "Rescue experiments were conducted to confirm the involvement of DKK1 in the tumor-suppressive functions of miR-376a in OS cells." (PMID 31525734, 2019). "The expression association between miR-217 and DKK1 was shown to be negative, while the expression correlation between CLRN1-AS1 and DKK1 in tumor samples was found to be positive." (PMID 31235696, 2019). "The number of CD8+ tumor-infiltrating lymphocytes (TILs) in invasive margin of CRC liver oligometastases was significantly higher in low serum DKK1 group (P = 0.042)." (PMID 31830954, 2019). "In that context, we thought it would be interesting to treat hepatic cancerous lines with the recombinant protein DKK1 to study its effect on tumor progression." (PMID 31568519, 2019). "We further confirmed that DKK1 promotes inflammation, tumor invasion and migration in both cell types." (PMID 31568519, 2019). "The results showed a significant elevation of TGF-β expression and secretion in the tumor microenvironment (TME) following treatment with the recombinant DKK1 protein." (PMID 31568519, 2019). "In these models, the high level of tumor cell-specific beta-catenin signaling is accompanied by high-level production of Wnt inhibitors DKK1 and WIF1, which reprogram the intra-tumor vascular phenotype by inhibiting beta-catenin signaling in ECs." (PMID 30932813, 2019). "Resumption of DKK1 expression reversed the tumor-suppressive activities of miR-376a overexpression in OS cells." (PMID 31525734, 2019). "In conclusion, the results of this study suggest that recombinant DKK1 facilitates tumor invasion and migration through remodeling the tumor microenvironment and inducing the secretion of proinflammatory cytokines." (PMID 31568519, 2019). "We also evidenced the expression of a number of genes, including ECMN and DKK1, possibly involved in the deregulation of tumor microenvironment." (PMID 31827721, 2019). "Elevated serum DKK1 were reported to be associated with poor prognosis among various tumors, whereas DKK1 was also reported to be a tumor suppressor gene conventionally." (PMID 31830954, 2019). "Not just regulating its own signaling pathway in cancer cells, DKK proteins, especially DKK1, were also reported to affect microenvironments to influence tumor progression." (PMID 31830954, 2019). "Next, to determine the role of DKK1 in tumor cell invasion, we performed the experiments using transwell chamber with Matrigel." (PMID 31285694, 2019). "This study implies that HOTTIP is somehow involved in tumor metastasis through down regulation of dickkopf WNT signaling pathway inhibitor 1 (DKK1) tumor suppressor gene." (PMID 32587834, 2019). "In contrast, other recent studies showed low DKK1 expression in GC samples, and that restoration of DKK1 in tumor cells inhibited tumor cell growth and invasion." (PMID 29720122, 2018). "It seems counterintuitive that MM cells require an active intrinsic canonical Wnt pathway to maintain cell survival and tumor growth, but at the same time also upregulate the canonical Wnt inhibitor Dkk1." (PMID 29776381, 2018). "Previous studies have reported that the putative Wnt target genes play oncogenic roles in cancer cell proliferation, migration, and invasion, whereas some genes such as DKK1 function as tumor suppressors." (PMID 29966001, 2018).